CSF1 (colony stimulating factor 1)
Diseases named in the same sentence as CSF1 in open-access papers (continued):
Sharing a sentence is not in itself a finding about the gene and the disease.
infection (continued). "Interestingly, IL-34 blockade did not alter infection susceptibility, indicating an immunosuppressive effect as observed with CSF-1 blockade can be prevented with anti-IL-34 treatment." (PMID 33162994, 2020). "Similarly, macrophage colony-stimulating factor 1 (CSF1) displayed a significant downregulated level during early infection stage (UC1) and it may facilitate compromised macrophage proliferation and autophagy functionality." (PMID 31614626, 2019). "To investigate whether the increased nucleotide diversities of samples CSF1, CSF2, and PLAS2 were due to mixed infections, we substituted variant alleles within distinct frequency ranges into the consensus sequences for the same samples and generated additional network phylogenies." (PMID 29986093, 2018). "Presently, we examine the roles played by the frog IL-34- and CSF-1-MΦs during chronic FV3 infections and establish the immunological parameters affected by skewing these frog MΦ populations during infections with this ranavirus pathogen." (PMID 34835105, 2021). "Our past work indicated that during acute infections, the IL-34- and CSF-1-MΦs, respectively, control and facilitate these FV3 infections." (PMID 34835105, 2021). "Our results showed that BAE cell infection by E. ruminantium resulted in the over-expression of several ECs surface proteins, such as ICAM1, VCAM1, CSF1, ESM1 and MCAM." (PMID 34073568, 2021). "In this analysis, the highest upregulation was observed for CCL5/RANTES and CSF1 in both CVS-11 and Z.Dog rabies infection, compared with mock infection." (PMID 32218146, 2020). "Instead the highest diversity in CSF1 and CSF2 was due to mixed infection with 2 or more different VZV clades." (PMID 29986093, 2018). "Importantly, selective deletion of Csf1 in CD4+ cells also resulted in significantly higher parasite burdens and delayed recovery from weight loss during the resolution phase of infection, directly demonstrating a role for MCSF derived from CD4+ cells in control of Plasmodium infection." (PMID 27923070, 2016). "Pattern "MTB" includes 177 genes whose expression levels changed specifically in response to infection with mycobacteria (e.g. NCF2, TNFSF13, CSF1)." (PMID 26586179, 2015). "Dermal CSF1-Fc treatment, in contrast, did not affect disease susceptibility despite increasing the abundance of MNP in the skin in the vicinity of the infection site." (PMID 33972588, 2021). "Because we observed extensive leukocyte infiltration into the kidneys of CSF-1-MΦ-enriched, FV3-infected frogs at later infection times, we next examined the kidneys of r-ctrl, rCSF-1- and rIL-34-administered animals after 28 dpi for expression of a panel of CC and CXC chemokine genes." (PMID 34835105, 2021). "We show that the CSF1-mediated increase in the abundance of MNP at the site of ID trypanosome infection did not affect the infection kinetics." (PMID 33972588, 2021). "Presently, we examined the roles of frog CSF-1- and IL-34-MΦs during long-term FV3 infection." (PMID 34835105, 2021). "In concert with CSF1 upregulation, other cytokines involved in microglial activation and proliferation, such as CCL1 and IL15, were found to be upregulated in both CVS-11 and Z.Dog strain infections." (PMID 32218146, 2020). "The genes, Ccl2, Ccl20, Csf1, Cx3cl1, Cxcl1, Cxcl3, Il6, Birc3, Map3k8, Nos2, Nfkb2, Tnfrsf1b, and Vcam1, played core roles in a PPI network, and interacted closely with other ones in the infection." (PMID 33042984, 2020). "In our analysis, we observe that a subset of these cytokines reported to be present in the serum also show transcriptional upregulations in PBMCs by 4 days post-infection (IL6, IL1B, IL1RN, CCL8, CXCL10) and by 7 days post-infection (CCL2, CCL3, CSF1, TNF, CXCL1, FAS and CXCL8)." (PMID 27595844, 2016). "Similar to mice lacking CSF-1, a ligand for CSF-1R, they succumbed to infection earlier than wild-type siblings." (PMID 26159717, 2015).
infection (continued). "Colony stimulating factor 1 (Csf1, Cytokine cluster)was induced to a greater extent in cPLA2α-/- RPM (10-fold)than cPLA2α+/+ RPM (3-fold).It promotes macrophage-lineage development but also recruits myeloid cellsduring inflammation and infection, and promotes their survival." (PMID 23950842, 2013).
neurodegenerative disease (17 papers, 2014 to 2025). A disorder of the central nervous system characterized by gradual and progressive loss of neural tissue and neurologic function. "Several of the most highly induced genes from the microglia gene sets (Clec7a, Cybb, Itgax, and Csf1) are specific markers of the “primed” microglia, a status associated with aging and neurodegenerative diseases." (PMID 31549781, 2019). "Interestingly, the activation of Akt in response to CSF1 in Trem2-deficient microglia indicates that CSF1 may be a potential therapeutic molecule for TREM2-loss-of-function neurodegenerative disease." (PMID 33841415, 2021). "Future prospective studies involving different potential confounding factors in populations of different ethnicities are merited to confirm the potential association between CSF1/CSF1R signaling and PD or other neurodegenerative diseases." (PMID 31554150, 2019). "A role of CSF1 in microglial activation and disease progression has been described in several models of injury and neurodegenerative diseases, but in few of them, the responsible cell type has been identified." (PMID 27846891, 2016). "Interestingly, genes associated with the recently characterized neurodegenerative disease-associated phenotype (DAM microglia), such as Clec7a, Csf1, Cd74, Cxcl10 and Cybb, were downregulated in 5xFAD/Gal3KO mice compared to 5xFAD mice." (PMID 31006066, 2019). "In neurodegenerative disease, CSF1R signaling activates proinflammatory processes through the regulation of CSF1 and IL-34 signaling." (PMID 33192177, 2020). "In neurodegenerative disease, CSF1R signaling might activate proinflammatory processes through regulating CSF1 and IL34 signaling." (PMID 32908485, 2020).
neurological disorders (11 papers, 2013 to 2024). "Further research should delve into the specific roles of associated molecules, such as CSF1 and CSF1R, in neurological diseases." (PMID 39113712, 2024). "Recent studies showed that the activation of CSF1R with CSF1 exerted anti-inflammatory effects in a variety of nervous system diseases." (PMID 32522286, 2020). "A positive correlation between m1A modification and gene expression was observed, and we selected genes related to neurological diseases (Bag3, Csf1, Cyp1b1, Egfr, Flnc, Lox, Mt1, Nid2, Rab3b, and Tubb4a) for analysis, with MeRIP-RT-PCR and qRT-PCR performed to verify this phenomenon." (PMID 37173310, 2023). "Furthermore, peripheral levels of CSF1, a CSF1R ligand, correlate with CSF1R levels in the CNS, and peripheral administration of CSF1 improves neurological disorders." (PMID 34512619, 2021). "This becomes very relevant because it was previously found that CSF1 signaling may contribute to the pathology of neurological disorders due to the altered microglia." (PMID 34899694, 2021). "The expression levels of CSF1 and CSF1R on neurons were significantly upregulated after various neurological diseases." (PMID 33101590, 2020). "As CSF1 regulates differentiation, maintenance and proliferation of myeloid lineage cells several pharmacological agents inhibiting CSF1R had been tested in animal models of neurological disorders." (PMID 30386212, 2018).
kidney diseases (8 papers, 2015 to 2025). "In kidney diseases, recent reports using mouse experimental models have revealed that not only CSF-1, but also IL-34 was expressed by damaged tubular epithelial cells (TECs) in ischemia/reperfusion (I/R) injury or lupus nephritis (LN)." (PMID 33428678, 2021). "The accumulation of macrophages is also attenuated in diverse animal models of renal diseases by the administration of an antibody against the receptor of CSF1." (PMID 32046074, 2020). "The analysis in biopsy-proven LN patients with active renal disease revealed elevated protein levels of CSF1, sIL15RA, sCD40, sCX3CL1, caspase 8, sIL18R1, bNGF, and GDNF compared to those without LN." (PMID 29026368, 2017). "When LN patients with active renal disease was compared to inactive LN subgroup, elevation of sIL15RA, CSF1, bNGF, sIL18R1, sCD40, sCX3CL1, and caspase 8 (P < 0.05), but not GDNF, in active LN patients was observed." (PMID 29026368, 2017). "Our serum protein analysis in LN patients with active renal disease revealed upregulated levels of CSF1, sIL15RA, sCD40, sCX3CL1, caspase 8, sIL18R1, bNGF, and GDNF compared to those without LN." (PMID 29026368, 2017). "Colony-stimulating factor 1 (Csf1) and C-X-C motif chemokine ligand 10 (Cxcl10) are expressed in renal epithelial cells and play crucial roles in producing and infiltrating inflammatory cells, thereby contributing to kidney disease development." (PMID 40516868, 2025). "Regarding CSF1, elevated serum levels in patients with SLE were shown to reflect kidney histopathology and to predict renal disease activity." (PMID 29026368, 2017). "Unlike CSF-1, no skewing has been observed between M1 and M2 Møs in experimental kidney disease models." (PMID 33428678, 2021).
cardiovascular disease (4 papers, 2014 to 2025). "Proteomic analysis in a subcohort revealed that higher levels of inflammatory and endothelial-related proteins (e.g., IL-18, TNF-R1/2, CSF-1, thrombomodulin, resistin) correlated with higher UPF intake, many of which were prospectively linked to cardiovascular disease." (PMID 41010537, 2025). "Intriguingly, in addition to its intrahepatic effects, systemic attenuation of CSF1 signaling may ameliorate cardiovascular disease to which PLWH with NAFLD are prone." (PMID 34006921, 2021).
adenocarcinoma (3 papers, 2014 to 2023). A common cancer characterized by the presence of malignant glandular cells. "CSF cytological analysis revealed the presence of a significant number of malignant cells (CSF1), and subsequent gastroscopy detected a poorly differentiated adenocarcinoma at the antrum." (PMID 37131253, 2023).
breast (3 papers, 2020 to 2023). "Playing a key role in this process, YAP1 could directly recruit M2 macrophages by stimulating the expression of chemokine ligand 2 (CCL2) and colony stimulating factor 1 (CSF1) for liver carcinogenesis." (PMID 35672802, 2022).
Respiratory Disease (2 papers, 2013 to 2022). "Respiratory disease biomarkers like ARG2, SCNN1G, EPB41L4B, CSF1, PTEN, TUBB1, and ESR2 were also detected." (PMID 24382964, 2013).
peripheral neuropathy (1 paper, 2022). A disorder affecting the peripheral nervous system. "The study demonstrated that the secreted proteoglycan isoform of CSF-1 mediates macrophage-related neural damage, while the cell-surface isoform of CSF-1 attenuates peripheral neuropathy." (PMID 35457072, 2022).
CSF1 also shares sentences with these, for which no sentence is quoted: HIV-1 infection (14 papers); fungal infections (9); pneumonia (8); autoimmune disease (7); psoriasis (7); psoriatic arthritis (6); acute myeloid leukemia (5); bacterial infection (5); endothelial dysfunction (5); head and neck squamous cell carcinoma (5); inflammation (5); amyotrophic lateral sclerosis (4); encephalitis (4); liver disease (4); lymph node metastasis (4); periodontal disease (4); sarcoidosis (4); ankylosing spondylitis (3); bladder cancer (3); brain disease (3); diabetic retinopathy (3); gout (3); Granuloma (3); idiopathic pulmonary fibrosis (3); infectious disease (3); Neonatal sepsis (3); Osteopenia (3); squamous cell carcinoma (3); Thrombocytosis (3); ampullary cancer (2).
A further 206 diseases each share a sentence with CSF1 in 2 papers or fewer.